FGFR3 (fibroblast growth factor receptor 3)
Diseases named in the same sentence as FGFR3 in open-access papers (continued):
Sharing a sentence is not in itself a finding about the gene and the disease.
tumor (continued). "It is now recognized that the FGFR3 signaling pathway overlaps with some oncogenic pathways in the human body, including the EGFR/RAS/PI3K/ERK/AKT pathway, and is correlated with the epithelial-to-mesenchymal transition of tumor." (PMID 35991125, 2022). "Consistently, the treatment of two FGFR3-mutated PDXs, one Ba/Sq and one LumP, both presenting high expression levels of FGFR3 protein compared to other non-mutated PDXs, with a pan-FGFR-inhibitor (BGJ398) only reduced tumor growth." (PMID 36033544, 2022). "NGS analysis of her GIST lesion revealed a quadruple wild-type tumor (no mutations in c-KIT, PDGFRA, SDH, RAS-P [RAS, BRAF, NF-1]) with a FGFR3 p.G145S mutation/variant which is of a germline rather than somatic variation." (PMID 35885469, 2022). "FGFR2 and FGFR3 mRNA expression levels were not significantly different between tumor and tumor-adjacent normal tissues (p = 0.97 and p = 0.9, respectively)." (PMID 36142417, 2022). "The pathways related to tumor progression, such as positive regulation of the MAPK cascade and FGFR (FGFR1, FGFR2, FGFR2c, FGFR3, and FGFR3c) ligand binding and activation, were significantly downregulated in the FSIP2-MT group (ES < 0, p < 0.05), suggesting a better efficacy." (PMID 34113648, 2021). "Considering the high expression levels of FGFR1 and FGFR3 across all EPN subtypes as well as the FGFR-driven malignant phenotype of ST-RELA and PF-A tumor cells, we tested the sensitivity of EPN cells towards a panel of small molecule FGFR tyrosine kinase inhibitors (FGFRi)." (PMID 34046693, 2021). "In contrast to UC tumor specimens, phosphorylation of members of the FGFR family of RTKs was lower in UC cell lines (FGFR1 25%, FGFR2 25%, FGFR3 25%, and FGFR4 0%) which may reflect the presence of stromal cells within the primary tumor samples evaluated." (PMID 34600548, 2021). "For instance, LumP tumours are strongly characterised by increased FGFR3 transcriptional activity as opposed to basal/squamous (Ba/Sq) tumours, which employ EGFR mechanisms." (PMID 32374509, 2020). "We found that the expression of hsa_circ_0068871 was positively correlated with T-stage (p = 0.044), N-stage (p < 0.001) and FGFR3 expression (p = 0.005) but not with age, sex, M-stage or tumour size." (PMID 30999937, 2019). "Unlike FGFR3 mutations, no relation of RAS mutational pattern with tumor grade and stage has been found." (PMID 31369573, 2019). "Noteworthy, FGFR-3 expressing primary tumors were also positive in 32/34 (94.1%) of the paired recurrent tumor samples; only 2/34 (5.9%) of the tumor pairs changed their expression profile from negative to positive or from positive to negative, respectively." (PMID 30894200, 2019). "FGFR3, observed in one tumor, was described only as a partner in oncogenic fusion, no missense variants have been reported until now as mediators of resistance." (PMID 31138260, 2019). "And 67.7 % (21/31) of high grade tumor cases were found to be negative whereas 32.3% (10/31) were positive for FGFR3." (PMID 31528172, 2019). "Indeed, the treatment of tumor‐bearing mice for 4 days with another pan‐FGFR inhibitor, BGJ398, which inhibited PDX tumor growth, decreased both MYC and FGFR3 levels in the tumors." (PMID 29463565, 2018). "With a reduction of E-cadherin protein in tumor samples compared with the normal, the expression of FGFR3 and E-cadherin exhibited a negative correlation, indicating that miR-24-3p-mediated FGFR3 signal facilitated metastasis in an EMT-related manner." (PMID 29850625, 2018). "However, only FGFR1 was expressed at high level, with a mean transcript expression of 187 RPKM in NRH-LS1 (and 143 in tumor B), compared to 0.3, 47, and 7.9 for FGFR2, FGFR3 and FGFR4, respectively." (PMID 27409346, 2016).
tumor (continued). "On the other hand, expression of a kinase mutant (K652E) of FGFR3 in the urothelium of transgenic mice failed to elicit urothelial proliferation, let alone tumor formation after 18 months, thus refuting a tumorigenic role of this particular mutation." (PMID 27157475, 2016). "In addition to the use of antibodies to target FGFR3, small-molecule inhibitors of the FGFR tyrosine kinase domain have demonstrated efficacy with several xenograft tumor models." (PMID 27056048, 2016). "It is, however, the compensatory tumor defense of the urothelial cells that counteracted the growth-promoting effects of the FGFR3 mutant, rendering the mutant non-tumorigenic." (PMID 27157475, 2016). "Indeed, genetic alterations in the EGFR, FGFR3, and RAS pathways are typical of tumor initiation and progression in bladder." (PMID 26925094, 2016). "FGFR3 protein expression was unknown for 27 OSCC and 29 OPSCC because all three TMA cores of the tumor were missing." (PMID 26711175, 2016). "Hypoxia-inducible factor-1 alpha (HIF-1α) protein expression is an unfavorable prognostic factor in bladder urothelial carcinoma as it can up-regulate FGFR3, VEGF, and GLUT-1 which contribute to tumor cell survival, tumor angiogenesis, and aerobic glycolysis in response to tumor hypoxia." (PMID 27557492, 2016). "In addition, we found that the Classical markers FGFR3, PDGFA, EGFR, AKT-2 and Nestin are highly expressed in intracranial tumor tissue derived from bulk tumor cells and Sp-GSCs, while there is lower expression in Ad-GSC intracranial tumors." (PMID 25955030, 2015). "- Some cell lines are more representative of the FGFR3-driven tumor pathway (RT112, MGH-U3, 97-7, BC61, RT4, SW-780, and UM-UC-6) whereas others are more representative of the tumor suppressor-driven pathways (5637, 92-1, 96-1, 97-18, 97-24, HT1376, SW-1710, UM-UC-1, UM-UC-13, and VM-CUB-2)." (PMID 25997541, 2015). "In non-muscle-invasive tumours where mutation was most frequent, mutations in the promoter of telomerase (TERT) (>80%) and activating mutations in FGFR3 (∼70%) are the most common events recorded to date." (PMID 24270882, 2014). "Since the whole tissue section was not available to be stained for FGFR3, we do not know if FGFR3 expression is homogenous throughout the tumor." (PMID 24846059, 2014). "Because FGFR3-positive RSCs are a useful model for CSCs, we examined the biological features of survivin and compared the therapeutic potentials of Surv.m-CRA against RSCs and progeny tumor cells." (PMID 24467821, 2014). "One of two FGFR3-mutant tumors for which both mRNA and IHC data were available had weak FGFR3 protein expression by IHC; the other tumor had negative FGFR3 expression." (PMID 24846059, 2014). "Since a compatible receptor of this inhibitor (FGFR3) is expressed in Cepi, CS2 may be a more conducive microenvironment for tumor growth than CS1." (PMID 23762861, 2013). "The tumor masses were not different from controls when Capan-2 cells overexpressed FGFR3-IIIc-KD, suggesting that the negative impact on tumor progression depended on FGFR3 tyrosine kinase activity." (PMID 23902722, 2013). "It is possible that opposite effects were FGF-dependent (FGF2 for the oncogenic effect and FGF9 for the tumor suppressive effect), the role of FGF2 being supported by previous studies (for example) but more work is needed to test the dependency of FGFR3 to FGFs." (PMID 23902722, 2013). "Activating mutations of Fibroblast Growth Factor Receptor 3 (FGFR3) have been found in 70–75% of Ta tumours, but they are absent in Cis and less frequent (15–20%) in invasive tumours." (PMID 24250280, 2013). "This proportion is lower than the 52% (95/183) of muscle-invasive tumours with wild-type FGFR3 observed, but not significantly so." (PMID 23272046, 2012).
tumor (continued). "We used the three groups, TaG3, T1, and T2–4, previously defined for the FGFR3-non-mutated pathway and the three groups, TaG1G2, T1, and T2–4 for the FGFR-mutated tumor pathway." (PMID 22724020, 2012). "The frequency of FGFR3 mutation was found to be very similar in pT1G2 and pTa G1G2 tumours, suggesting that most pT1G2 tumours are derived from the Ta pathway rather than the CIS pathway." (PMID 23272046, 2012). "All the tumours identified with FGFR3 or HRAS mutations expressed SSX2-4 (7/7), whereas all OCT2-positive tumours were mutation-negative (4/4); however, these differences were not statistically significant." (PMID 21706474, 2011). "Expression of total FGFR3 mRNA was found to be downregulated in 20 of 22 tumour specimens, resulting in a significant overall reduction in tumours compared with non-malignant colon tissue specimens (P=0.0015)." (PMID 20234367, 2010). "Notably, a fraction of free A2 passively diffuses into the tumor microenvironment, demonstrating a potent bystander effect that effectively eliminates adjacent FGFR3‐negative tumor cells." (PMID 41168906, 2026). "Targeting FGFR3 with specific inhibitors such as Small Molecule Tyrosine Kinase Inhibitors (Erdafitinib, Infigratinib) or monoclonal antibodies (Vofatamab) has shown efficacy in inhibiting aberrant signaling pathways like MAPK-ERK and JAK-STAT, thereby suppressing tumor growth." (PMID 40943615, 2025). "In summary, FGFR3 alterations play a crucial role in tumor initiation but may not be the primary drivers of stage progression." (PMID 39410541, 2024). "Studies suggest that the anti-tumor response to ICIs may not differ significantly between patients with and without FGFR3 alterations." (PMID 39764422, 2024). "Although FGFR3 mutation presumably initiated cancer development in these cancers, it has been suggested that at some point during tumor progression, EGFR signaling may have increased to a level where it repressed mutant FGFR3 expression and dominated the downstream signaling." (PMID 39031286, 2024). "The present study demonstrated that the biological characteristics of UTUC tumor origin shifts from luminal to basal-like features with progression to MIBC, but FGFR3 expression taken over from UTUC origin may comprise a favorable entity compared to primary MIBC." (PMID 35563543, 2022). "This cluster reduces tumor growth by inhibiting proteins involved in important cellular processes, including homeobox A1 (HOXA1), mammalian target of rapamycin (mTOR), insulin-like growth factor binding protein 1 (IGFBP1), and fibroblast growth factor receptor 3 (FGFR3)." (PMID 35327452, 2022). "Moreover, both BPV-E4- and BPV-E1^E4-mediated nucleofection of equine ACFCs brought about the upregulation of FGFR3 and FGF12 (fibroblast growth factor receptor 3 and fibroblast growth factor 12), which are known as factors promoting tumor growth and metastasis." (PMID 35216085, 2022). "Putative oncogenic and targetable mutations could be found in individual tumor samples in FGFR2 (SNUC, SNSCC non-keratinizing), FGFR3 (SNSCC-associated with ISP), MAP1K2 (SNAC), MET (ISP-associated SNSCC), MAP2K1 (SNAC) and HRAS (SNSCC keratinizing and ITAC)." (PMID 34885191, 2021). "Moreover, the sample sizes of some tumor types from this study were not sufficient, and the full FGFR3 alteration spectrum was difficult to achieve in these cancer types." (PMID 34160364, 2021). "Tumor purity scores, calculated using the ESTIMATE tool, were associated with FGFR3, but not PIK3CA or TERT mutations, which could be explained by a positive association between the Uro subtype and tumor purity." (PMID 31609466, 2020). "This suggests that the role of ETV5 in bladder carcinogenesis may not be limited to FGFR3-mutant tumours but may also be relevant to tumours with other alterations resulting in MAPK/ERK activation, such as RAS mutations." (PMID 30952872, 2019).
tumor (continued). "The RNA expression of FGFR3 in these tumours is not reported in the trial." (PMID 30258198, 2018). "Due to their low FGFR3 expression, patients with CDKN2Ahigh tumours presumably do not seem to be suitable candidates for a therapy targeting FGFR3, whilst patients with a high FGFR3 expression might benefit from such an approach." (PMID 30258198, 2018). "Furthermore, there was a significant positive correlation between the expression of FGFR1-FGFR2 (ρ = 0.24, p = 0.026) and FGFR2-FGFR3 (ρ = 0.23, p = 0.031) in tumor tissues, while FGFR1 expression was inversely correlated with FGFR3 expression (ρ = −0.30, p = 0.005)." (PMID 27669755, 2016). "Silencing FGFR3 did not affect cell survival or tumor growth." (PMID 23185502, 2012). "Despite the association of FGFR3 alternations with a non-T cell-inflamed tumor microenvironment and the reduced sensitivity to immune checkpoint inhibitors (ICIs), recent studies have indicated that patients with BC respond equally to ICIs regardless of FGFR3 status." (PMID 40603902, 2025). "Diverse treatment outcomes were observed in Sq-NSCLCs with other FGFR variants: SD (4.1 months PFS and 20% tumor shrinkage) was reported in one patient (6.6%) with simultaneous FGFR1 missense variants: D93Y and H841Y, whereas no response was reported in a patient (1/27, 1.4%) with FGFR3 fusion." (PMID 35402233, 2022). "As previous studies on FGFR3 genetic alterations in cancer are limited to the individual cancer types and/or to the insufficient sample sizes, a comprehensive analysis and view across various tumor types of TCGA to investigate their significance have not been explored." (PMID 34160364, 2021). "However, the heterogeneity of FGFR3 genotypes within a tumor has not been adequately addressed and may negatively impact therapeutic response." (PMID 33243261, 2020). "However, we also found that the mRNA levels of Fgfr3 in the Renca model and Fgfr1 and Fgfr4 in the B16F10 model were significantly upregulated by chronic expression of VEGFR2-Fc, consistent with previous reports that FGFR1, 3, and 4 also play a critical role in tumor angiogenesis." (PMID 32076044, 2020). "Secondly, the increased frequency of rs798766[T] may accelerate the tumor formation through upregulating the expression of TACC3 which increases the microtubule dynamic stability and massively promotes cell division, possibly enhanced by simultaneously stimulated FGFR3 activation." (PMID 28655970, 2017). "Expression of FGFR3 was evident as membranous and cytoplasmic immunoreactivity, scored in a semi-quantitaive scoring system: 0 = all tumor cells negative, 1 = weak positivity in more than 10% of tumor cells, 2 = moderate positivity and 3 = strong positivity/overexpression." (PMID 23809295, 2013). "That fusion-positive case, which has been reported as SDC, harbored additional driver alterations (BRCA2 and PTEN) in addition to the FGFR3::TACC3 fusion; the morphology of the tumor has not been illustrated." (PMID 39387893, 2025).
tumor (continued). "In BCX.080, a model with FGFR3 and FGFR4 RNA overexpression and without a detectable genomic alteration, futibatinib had modest tumor growth inhibition without significantly prolonging EFS." (PMID 37980453, 2023). "We found FGFR1 transcript to be selectively elevated in cells from spindloid tumours when compared to all other tumour types and normal mammary gland, while FGFR2 and FGFR3 were not modulated and FGRF4 was undetectable (not shown)." (PMID 33772015, 2021). "This, in combination with the absence of FGFR3 and CCND1 protein expression, suggests that these tumours have a GU tumour‐cell phenotype." (PMID 28195647, 2017). "The basal/SCC‐like cases in the same consensus cluster showed almost no expression of FGFR3 and CCND1, whereas the reverse was seen for KRT5 and CDH3 tumour‐cell expression." (PMID 28195647, 2017). "Fibroblast growth factor receptor 3 (FGFR3) protein expression showed no relevant relationship with clinicopathological variables, including differentiation grade, tumor stage, and regional lymph node metastases." (PMID 26711175, 2016). "As expected, neither mutant FGFR3 or upregulated FGFR1 was sufficient alone to confer on normal urothelial cells a fully transformed phenotype, such as anchorage-independent growth or the ability to form tumours in nude mice." (PMID 22899908, 2012). "The GU‐Uro tumours differed from Uro tumours by increased proliferation, immune and extracellular matrix (ECM) mRNA signatures, but protein expression levels of the canonical Uro genes FGFR3, CCND1 and TP63 were not different in the Uro versus GU‐Uro groups of tumours." (PMID 28195647, 2017).